IFRD2 (interferon related developmental regulator 2)
Description:
Ribosome-binding protein that acts as an inhibitor of mRNA translation by promoting ribosome inactivation. Associates with the P- and E-sites of the ribosome and inserts a C-terminal helix into the mRNA exit channel to preclude translation (By similarity).
Synonyms: SKMc15; SM15; IFNRP
Tractability: PROTAC: ubiquitination databases record sites on it; its protein half-life has been measured.
Gene: Protein-coding gene on chromosome 3 (50,287,732 to 50,292,918, reverse strand). Ensembl gene ENSG00000214706.
Subcellular location (Human Protein Atlas): Nucleoplasm
Gene Ontology:
Molecular function: protein binding; ribosome binding; translation repressor activity
Biological process: negative regulation of translation
Cellular component: nucleus
Genetic constraint (gnomAD): Loss-of-function variants: 35 observed, 43.42 expected, observed/expected ratio (o/e) 0.81, 90% interval 0.62 to 1.07. The upper end of that interval is the gene's LOEUF score, 1.07, which puts it in group 4 of 6, group 1 being the genes least tolerant of losing a copy. Missense variants: 561 observed, 565.66 expected, observed/expected ratio (o/e) 0.99, 90% interval 0.93 to 1.06. Synonymous variants: 275 observed, 232.58 expected, observed/expected ratio (o/e) 1.18, 90% interval 1.07 to 1.31.
Homologues: Orthologues: chimpanzee IFRD2 (99% identical), macaque IFRD2 (98% identical), pig IFRD2 (90% identical), guinea pig IFRD2 (89% identical), rat Ifrd2 (88% identical), mouse Ifrd2 (88% identical), dog IFRD2 (85% identical), tropical clawed frog ifrd2 (58% identical), zebrafish ifrd2 (56% identical), Drosophila melanogaster Ifrd1 (37% identical), Caenorhabditis elegans F58B3.6 (26% identical). Paralogues in human: IFRD1 (50% identical).
Diseases named in the same sentence as IFRD2 in open-access papers:
IFRD2 is named in the same sentence as 5 diseases in open-access papers, as found by Europe PMC text mining. Sharing a sentence is not in itself a finding about the gene and the disease. The quoted sentences say what the papers report.
hypertriglyceridemia (1 paper, 2023). A laboratory test result indicating elevated triglyceride concentration in the blood. "The results presented here implicate that Ifrd1 and Ifrd2 play a up to now unknown role in the regulation of Cd36 and therefore possibly contribute to Cd36-related pathogenesis of human metabolic diseases, such as hypoglycemia, hypertriglyceridemia, and disordered fatty acid metabolism." (PMID 37603466, 2023).
Obesity (1 paper, 2023). Accumulation of substantial excess body fat. "Mice deficient in both Ifrd1 and Ifrd2 (dKO) had severely reduced adipose tissue and were resistant to high-fat diet-induced obesity." (PMID 37603466, 2023). "Experimental data presented here show that simultaneous depletion of Ifrd1 and of its orthologue Ifrd2, a protein recently identified as a translational inhibitor, caused severe reduction of adipose tissues and resistance against high fat-induced obesity in mice." (PMID 37603466, 2023). "It is possible that due to the reduced Cd36 expression levels in intestines, Ifrd1 Ifrd2 dKO mice accumulated lower amounts of body fat and were resistant to diet-induced obesity also because of limited intestinal fat uptake." (PMID 37603466, 2023).
IFRD2 also shares sentences with these, for which no sentence is quoted: tumor (2 papers); Hypoglycemia (1); metabolic disease (1).